SNAI1 (snail family transcriptional repressor 1)
Diseases named in the same sentence as SNAI1 in open-access papers (continued):
Sharing a sentence is not in itself a finding about the gene and the disease.
glioma (continued). "Mechanistically, IF1 may promote glioma cell migration and invasion through the NF-κB/Snai1 axis." (PMID 26622799, 2015). "Thus, the present results indicate that IF1 may promote glioma metastasis via the NF-κB/Snai1 signaling pathway." (PMID 26622799, 2015). "The NF-κB/Snai1 axis may be involved in the IF1-mediated metastasis of glioma." (PMID 26622799, 2015). "miR-128 plays a negative regulatory role in the SNAI1/miR-128/SP1 axis, counteracting this role of SNAI1 in promoting glioma progression and inhibiting glioma aggressiveness." (PMID 36479040, 2022). "Immunohistochemistry and in situ hybridisation staining were used for quantifying SNAI1, SP1 and miR-128 expression levels in human glioma samples." (PMID 24959930, 2014). "IHC showed that the SNAI1 and SP1 staining of grade I to II (low grade gliomas) was weaker than that of grade III and IV (high grade gliomas) tissues." (PMID 24959930, 2014). "Immunohistochemistry and in situ hybridisation analysis of SNAI1, SP1 and miR-128 unraveled their expression levels and correlations in glioma samples." (PMID 24959930, 2014). "We also found the total numbers of sole activators of FOXM1, PDGFRA, OPN, CYCLIN_D, CYCLIN_E, BMI, SNAI1, JAGGED2, SFRP were increased in Glioma scenario as compared to the canonical HH pathway." (PMID 23935937, 2013). "Another study revealed that a highly invasive glioma cell line, U87R4, harbored increased expression of the FZD4 receptor, which was found to promote the acquisition of a mesenchymal phenotype (CD44 and SNAI1 expression)." (PMID 28821904, 2018). "We propose that the SNAI1/miR-128/SP1 axis, which plays a vital role in glioma progression, may come to be a clinically relevant therapeutic target." (PMID 24959930, 2014). "SNAI1 specific miRNA signature in human glioma tissues (negative correlation)." (PMID 24959930, 2014). "As EMT induction factor, transcription factors, the expression of SNAI1, SNAI2, TWIST1, and PDGFB was significantly higher in high-grade, elderly glioma patients, IDH-wildtype, 1p19q non-codel glioma patients." (PMID 32154177, 2020).
cervical cancer (38 papers, 2015 to 2025). A primary or metastatic malignant neoplasm involving the cervix. "Studies have shown that highly expressed PD-L1 in cervical carcinoma cells can promote the growth and metastasis of cervical cancer through the ITGB4/SNAI1/SIRT3 pathway." (PMID 36478746, 2022). "A de–regulation of Wnt signaling was also reported for liver and cervical cancer, associated with a reduction of EMT markers such as SNAI1, SNAI2, ZEB1 or VIM in cervical cancer–derived cell lines." (PMID 34062997, 2021). "It suppressed cervical cancer cell migration by inhibiting the expression of positive regulators of epithelial-mesenchymal transition SNAI1 and VIM." (PMID 31527550, 2019). "It was reported that PD-1 could promote lymph node metastasis in cervical cancer via activating integrin β4/SNAI1/SIRT3 axis." (PMID 34666670, 2021). "Furthermore, the mRNA expression of TGFB1 was negatively correlated with the expression of METTL3, while positively correlated with the expression of SNAI1 in 169 cases of cervical cancer patients." (PMID 31991845, 2020). "Our findings suggest that CA, by suppressing VEGFA, may possibly contribute to the reduction of SNAI1 transcription in cervical cancer cells, but further mechanistic study is needed." (PMID 29337896, 2018). "We then confirmed the expression changes of some of the identified marker genes (OSMR, SNAI1, and HK2) for the cluster in HeLaS3 and SiHa cervical cancer cell lines by RT-qPCR." (PMID 36551576, 2022). "Specifically, it is shown that SNAI1, along with ZEB1, regulated the epithelial–mesenchymal transition and was then involved in the metastasis of cervical cancer." (PMID 34149809, 2021). "Many cell culture experiments and in vivo studies have demonstrated that inhibition of E-cadherin expression by its transcriptional suppressor SNAI1 is a key process driving EMT, also in cervical cancers." (PMID 29337896, 2018). "Crinamine induces cell apoptosis without promoting DNA double strand breaks and suppresses cervical cancer cell migration by downregulating SNAI1 and VIM expression, positive regulators of epithelial-mesenchymal transition." (PMID 38751791, 2024). "SNAI2/Slug and SNAI1 were reported to be upregulated by TGF-β treatment of cervical cancer cells." (PMID 36766756, 2023). "The effect was less prominent in cervical cancer HeLa cells—we observed SNAI1/SNAI2 upregulation (though not so prominent as in A549 cells) in HeLa cells overexpressing HSAT2 without significant changes in cell morphology." (PMID 37108080, 2023). "CLDN1 had a direct or an indirect interaction with SNAI1 in SiHa cells, which was demonstrated by immunoprecipitation; this result suggested that the consequence of overexpression of CLDN1 could increase the invasion of cervical cancer cells." (PMID 27974683, 2016).
renal fibrosis (38 papers, 2013 to 2025). A final common manifestation of a wide variety of chronic kidney diseases characterized by glomerulosclerosis and tubulointerstitial fibrosis. "In our study, we demonstrated that HRAS activated RREB1, enhancing SMAD2/3 association with Snai1 and Has2cis-regulatory regions during renal fibrosis." (PMID 39913299, 2025). "TGF-β1 is the master regulator of renal fibrosis and is in strong association with Snai1 and the partial EMT process." (PMID 33414422, 2021). "During renal fibrosis, Snai1 not only acts as a target of WNT/β-catenin to regulate the EMT process, but also cooperates with WNT ligands to induce signaling." (PMID 40012992, 2024). "In STZ-induced diabetic mice, activation of IGF-1 promoted renal fibrosis by upregulating SNAI-1." (PMID 36225569, 2022). "Here, we showed that Bay11-7082, the NF-κB inhibitor, could alleviate the partial EMT and renal fibrosis induced by Snai1 upregulation, as well as resolve the inflammatory response in the interstitium." (PMID 33414422, 2021). "We then demonstrated that the regulation of Snai1 in UUO model not only changed the EMT process, but also led to changes in cell cycle arrest, interstitial inflammation, and renal fibrosis in parallel." (PMID 33414422, 2021). "Snai1 controlled the partial EMT process, and led to parallel changes in renal fibrosis, G2/M arrest, and inflammation." (PMID 33414422, 2021).
lung adenocarcinoma (34 papers, 2012 to 2025). A carcinoma that arises from the lung and is characterized by the presence of malignant glandular epithelial cells. "It has been reported to upregulate EMT-transcription factors like Snai1 and Snai2 in breast and lung adenocarcinoma." (PMID 37025658, 2023). "PIK3C2B expression showed significant positive correlations with key EMT regulators: SNAI1 (r = 0.11, p = 0.00098), VIM (r = 0.21, p = 1e-10), ZEB1 (r = 0.37, p = 6.7e-33), and TWIST2 (r = 0.11, p = 0.00034) in TCGA lung adenocarcinoma samples." (PMID 41362647, 2025). "To validate the presence of differential expression between SNAI1 and SNAI2 in other cancers, we subjected the lung adenocarcinoma cell line, A549 to TGFβ treatment." (PMID 31165775, 2019). "Expression of TWIST1, mesenchymal (CDH2, VIM, SNAI1, ZEB1) and epithelial (CDH1, JUP) markers in lung adenocarcinoma cell lines." (PMID 22272264, 2012). "However, SNAI1 expression was significantly lower in kidney renal papillary cell carcinoma (KIRP), liver hepatocellular carcinoma (LIHC), lung adenocarcinoma (LUAD), lung squamous cell carcinoma (LUSC), Prostate adenocarcinoma (PRAD), thyroid carcinoma (THCA), corpus Endometrial Carcinoma (UCEC)." (PMID 32833672, 2020). "In contrast, expression levels of the remaining factors were not different between tumours and normal tissues (ZEB2, SNAI1 and SLUG), or even higher in tumours (TWIST), implying that these factors may not be the primary regulators of EMT in lung adenocarcinomas." (PMID 27456471, 2016).
breast tumors (33 papers, 2009 to 2025). "In these primary breast tumors, SNAI1 transcription was also frequently induced (FC>10 in 68.6%, n = 67) in line with previous reports." (PMID 24638100, 2014). "Therefore, our results, in conjunction with other published data, suggest a SNAI1/DDR2 mutual regulation loop that facilitates the sustained activation of the DDR2 signaling pathway in breast tumor metastatic progression." (PMID 36713812, 2022). "Detection of the first distant recurrence in the liver was associated with absence of SNAI1 expression in the breast tumor." (PMID 21914172, 2011). "Interestingly, the association between high SNAI1 expression and low CTCF has also been observed clinically, as we found a significant correlation between low CTCF and high SNAI1 expression in patients’ breast tumors." (PMID 36037342, 2022). "Accordingly, we found a positive correlation between FOXA1 and AR expression in breast tumors, while transient silencing of FOXA1 led to decreased AR mRNA expression levels in SNAI1-KO cells." (PMID 36171192, 2022). "In our primary breast tumor specimens, correlation between mtDNA content and the expression of ESRP1 (ρ = 0.25, P < 0.001), SNAI1 (ρ = 0.23, P < 0.001) and TGFB1 (ρ = 0.18, P < 0.01) was statistically significant after correction for multiple testing." (PMID 27081694, 2016). "This revealed that both EPI (e.g. LLGL2, CLDN4, KRT7, ST14) and MES (e.g. SNAI1, VIM, AP1M1) genes positively correlated with PIEZO1 expression across all quintiles, whilst markers of luminal breast tumors (ESR1, FOXA1, PGR) negatively correlated in all instances." (PMID 38632473, 2024). "In breast tumor cells, DDR2 regulates tumor cell collective invasion by sustaining a SNAIL1 (SNAI1)-mediated epithelial–mesenchymal transition (EMT) invasive program, particularly in keratin 14 (KRT14)-positive leader cells, as well as full activation of collagen-binding integrins." (PMID 34477203, 2021). "In this study, SYNJ2BP was shown to enhance breast tumor metastasis and EMT by activating SNAI1." (PMID 29163781, 2017). "In conclusion, both SNAI1 and SNAI3 gene expressions are induced in primary breast tumors compared to normal mammary epithelial cells, suggesting that likewise SNAIL1, SNAIL3 may also contribute to breast tumorigenesis." (PMID 24638100, 2014). "The liver was the first distant metastatic site in 28 (19.3%) of the 145 women with SNAI1-positive cancer as compared with 25 (36.2%) of the 69 patients whose breast tumor did not express SNAI1 (P = 0.007)." (PMID 21914172, 2011).
bladder cancer (29 papers, 2011 to 2025). "In bladder cancer tissues, the expression of hnRNP F is also significantly up-regulated, enhances stability, and promotes the translation of Snai1 mRNA, which promotes EMT and is significantly associated with poor prognosis among bladder cancer patients." (PMID 36831493, 2023). "In bladder cancer, SNAI1, SNAI2 and TWIST are differentially expressed and TWIST and SNAI2 expression have been shown to play an important role in tumor progression and metastasis formation." (PMID 25247809, 2014). "High expression of KLFC1 promoted the phosphorylation of glycogen synthase kinase 3 beta (GSK3β) and enhanced the expression of SNAI1 (encoding snail family transcriptional repressor 1) via protein kinase B (AKT) activation, which induced bladder cancer cell growth and EMT." (PMID 35811688, 2022). "Thus, we included TGFBR, which is connected to SMADs, and the chemokine (C-X-C motif) receptor 1 (CXCR1) connected to ZEB1 and SNAI1 in the bladder cancer model." (PMID 28775339, 2017). "Overexpression of SNAI1 and ZEB1 transcripts were detected in all three bladder cancer cell lines stimulated with CAF-CM." (PMID 26152796, 2015). "Correlation analysis in bladder cancer samples from TCGA BLCA demonstrated a positive correlation between mRNA levels of IGF2BP3 and SNAI1 (Snail), SNAI2 (Slug), CDH2 (N-cadherin), VIM (vimentin), and MMP9, further supporting the association between IGF2BP3 and EMT-related markers." (PMID 38504159, 2024).
glioblastoma (29 papers, 2012 to 2025). The most malignant astrocytic tumor (WHO grade IV). "Then, we examined NOTCH1, CDH2 and SNAI1 three-gene signature in the Glioblastoma Multiforme (GBM) cohort (TCGA, Provisional, n = 577) and demonstrated its association with decreases in DFS (P < 0.05)." (PMID 30170559, 2018). "In particular, SNAI1 expression is significantly elevated in glioblastoma." (PMID 24959930, 2014). "SNAI1 inhibition can decrease invasion and migration of glioblastoma cells in vitro." (PMID 23846349, 2013).
liver cancer (26 papers, 2011 to 2025). An epithelial or non-epithelial malignant neoplasm that arises from the liver. "Additionally, our previous study found that SNAI1 is abnormally highly expressed in human liver cancer tissues by western blotting, and SNAI1 is remarkably associated with poor prognosis and recurrence of HCC by ROC and survival analysis." (PMID 27239445, 2016). "In summary, we found that VRK1 interacted with and phosphorylated the CHD1L at S122 site to regulate SNAI1 expression, thus promoting the proliferation, migration and tumor growth of liver cancer cells." (PMID 40234378, 2025). "VRK1 phosphorylates CHD1L at serine 122 to induce the expression of SNAI1, thereby promoting the proliferation, migration and tumor growth of liver cancer cells." (PMID 40234378, 2025). "Further, a ceRNA network between miR-199a-5p, LINC01133, and SNAI1 was identified to regulate the growth, invasion, and metastasis of liver cancer cells." (PMID 35747817, 2022). "In addition, further studies examined that VRK1 promoted the proliferation and migration of liver cancer cells by upregulating the expression of SNAI1 in vitro." (PMID 40234378, 2025). "Targeting ANGPTL3/SNAI1/CPT1A axis may serve as a therapeutic approach to improve prognosis of liver cancer patients with sorafenib resistance." (PMID 39708716, 2025). "We found that mRNA levels of SNAI1 were increased in ANGPTL3-depleted liver cancer cell lines." (PMID 39708716, 2025). "In addition, miR-203 downregulation has been described in various cancers including esophagus, cervix, prostate, breast, and liver cancer, and miR-203 inhibits cancerous invasion by targeting SNAI1, SNAI2, ZEB2, and VEGFA." (PMID 26882562, 2016). "Our results uncover a mechanism through which ANGPTL3 reduces SNAI1/CPT1A expression, thereby suppressing tumor metastasis and drug resistance in liver cancer." (PMID 39708716, 2025). "It sponges up miR-199a-5p, leading to an increase in the expression of SNAI1, thereby inducing EMT in liver cancer cells." (PMID 35747817, 2022). "TRERNA1 is also upregulated in liver cancer, and reduces the H3K9 methylation of the promoter region of CDH1 genes to regulate the EHMT2/SNAI1 complex, resulting in the increased tumor metastasis." (PMID 35034562, 2022). "The expression of 5 TGFβ-responsive genes (IL11, SERPINE1, SMAD7, SNAI1 and TGFBI) was further validated in other liver cancer cell lines." (PMID 34571856, 2021). "ANGPTL3 increases sorafenib sensitivity by inhibition of SNAI1 and CPT1A in liver cancer." (PMID 41562091, 2025). "We found that SNAI1 is highly expressed in the tissues of liver cancer compared with adjacent nontumor tissues." (PMID 27239445, 2016). "In liver cancer, IF1 propitiates metastasis and angiogenesis through non-canonical signaling of the NFκB pathway to Snai1, which mediates epithelial mesenchymal transition, and to VEGF, that induces angiogenesis." (PMID 26595676, 2016).
non-small cell lung carcinoma (21 papers, 2013 to 2025). A group of at least three distinct histological types of lung cancer, including non-small cell squamous cell carcinoma, adenocarcinoma, and large cell carcinoma. "In addition, vimentin and SNAI1 have also been associated with the malignant phenotype of non-small cell lung cancer (NSCLC)." (PMID 36766756, 2023). "Tumor suppressor FBXW7 triggering ubiquitin-dependent degradation of manyoncogenic factors such as Myc, c-Jun, Cyclin E, and Notch1 is responsible forthe degradation of Snai1 in non-small cell lung cancer cells." (PMID 33173593, 2020). "MSI2 depletion significantly down-regulates EMT markers (TGF-β receptor 1, SMAD3, SNAI1 and SNAI2) to inhibit non-small cell lung cancer metastasis." (PMID 31952541, 2020).
osteosarcoma (21 papers, 2017 to 2026). A usually aggressive malignant bone-forming mesenchymal neoplasm, predominantly affecting adolescents and young adults. "In osteosarcoma, TGFβ can escape miR-124 negative regulation and trigger SNAI1 expression to cause epithelial marker downregulation while upregulating mesenchymal markers, inducing EMT in vivo." (PMID 40442778, 2025). "Tim‐3 downregulation significantly suppressed osteosarcoma cell (MG‐63) proliferation and metastasis via inhibition of the NF‐κB/SNAI1 signaling pathway causing epithelial differentiation." (PMID 28556516, 2017). "For example, in osteosarcoma, SNAI1 expression is associated with miR-145 downregulation." (PMID 40442778, 2025). "In a study using 83 osteosarcoma tissues, the expression of Snai1/Slug/Twist1 was correlated with that of EPB41L3." (PMID 37373330, 2023). "Deletion of EPB41L3 suppresses cell growth in OS, and intriguingly, reduction of EPB41L3 expression stabilizes Snai1 protein, and in turn, promotes osteosarcoma invasion and metastasis through activation of Snai1-induced EMT." (PMID 33323539, 2020). "A recent study shows that TGF‐β treatment can trigger MT of osteosarcoma cells in vitro involving estrogen‐related receptor α‐dependent activation of SNAI1." (PMID 28556516, 2017). "Indeed, miR-145 overexpression induced by a miR-145 agomiR resulted in a dampened ability of osteosarcoma cells to migrate and invade in vitro, attenuated SNAI1 and CDH1 expression, thus reverting EMT." (PMID 40442778, 2025). "In summary, our results suggest that EPB41L3 could play both pro-tumorigenic and anti-metastatic roles in osteosarcoma, and exert its metastasis-suppressive function through inhibiting the Snai1-mediated EMT process." (PMID 33323539, 2020). "It has been shown in osteosarcoma that the silencing of AMF/PGI reduces the production and secretion of TGF‐β2 and TGF‐β3 resulting in downregulation of SNAI1 that can elevate E‐cadherin expression leading to MET." (PMID 28556516, 2017).